MUC16 (mucin 16, cell surface associated)
Diseases named in the same sentence as MUC16 in open-access papers (continued):
Sharing a sentence is not in itself a finding about the gene and the disease.
ovarian carcinoma (continued). "The ovarian cancer biomarker CA125/MUC16 is a transmembrane mucin that binds to mesothelin, a GPI-linked protein expressed by mesothelial cells." (PMID 22527451, 2012). "The usefulness of MUC16 as a target antigen in ovarian carcinomas is hampered by cleavage and secretion of its extracellular domain." (PMID 22481932, 2012). "As a tumor marker for ovarian cancer, CA 125 is a MUC16 glycoprotein comprised of a carboxyl terminus anchor region, a dominant repeat region, and a predominantly O-glycosylated region." (PMID 21906357, 2011). "In conclusion, we provide direct evidence that the knockdown of CA125/MUC16 in NIH:OVCAR3 ovarian cancer cells alters epithelial and mesenchymal markers, cell motility and migration." (PMID 21326240, 2011). "Our data now demonstrates that MUC16 expressing ovarian cancer cells are protected from recognition by NK cells." (PMID 20089172, 2010). "The identification of Siglec-9 as the receptor for MUC16 also has significance in the development of a novel test to monitor ovarian cancer progression." (PMID 20497550, 2010). "By serving as a ligand of mesothelin, MUC16 mediates binding between ovarian cancer cells and the mesothelium." (PMID 20497550, 2010). "These knockout mice provide a unique platform for future studies to identify the role of CA125/MUC16 in organ homeostasis and ovarian cancer." (PMID 19262696, 2009). "CA125/MUC16 has served as a very useful serum marker to monitor the progression of ovarian cancer or response to treatment." (PMID 19262696, 2009). "In spite of the utility of CA125 in the clinic, the biological functions of CA125/MUC16 in normal physiology and ovarian cancer are still poorly understood." (PMID 19262696, 2009). "It forms a strong and specific complex with MUC16, which is also highly expressed on the surface of mesothelioma and ovarian cancer cells." (PMID 19128473, 2009). "These mice will also be a useful resource for future studies to provide insights into the role of MUC16 in organ homeostasis and ovarian cancer both in vitro and in vivo." (PMID 19262696, 2009). "The high molecular weight of MUC16 requires the use of extensive molecular biological approaches to study the importance of this mucin in the pathogenesis of ovarian cancer." (PMID 19538730, 2009). "We demonstrate that murine Muc16 is expressed by mouse ovarian cancer cells as an ~250 kDa glycoprotein that carries both O-linked and N-linked oligosaccharides." (PMID 19538730, 2009). "Cancer antigen 125 (CA125) is a blood biomarker that is routinely used to monitor the progression of human epithelial ovarian cancer (EOC) and is encoded by MUC16, a member of the mucin gene family." (PMID 19262696, 2009). "Recent studies indicate that MUC16 is not only important as a tumor marker but also promotes peritoneal metastasis of ovarian cancer and suppresses the cytolytic responses of human natural killer cells." (PMID 19538730, 2009). "The binding of MUC16 to mesothelin is of particular interest because this interaction implicates a role for MUC16 in dissemination of ovarian cancer cells to the peritoneal cavity." (PMID 19262696, 2009). "MUC16 mucin interacts with the glycosylphosphatidylinositol anchored glycoprotein mesothelin at high affinity and facilitates the peritoneal metastasis of ovarian cancer cells." (PMID 20034397, 2009). "No combination of markers provided a significantly better sensitivity at 98% specificity than the best individual marker, MUC16, in distinguishing all ovarian cancers or serous ovarian cancers from controls." (PMID 18612378, 2008). "The binding between the MUC16 expressing ovarian tumor cells and the A431-Meso+ cells occurs even in the presence of ascites from patients with ovarian cancer." (PMID 17067392, 2006). "The ovarian cancer cells sloughing off from the tumor are bathed in peritoneal fluid that contains high amounts of MUC16 (; Patankar, Belisle, and Gubbels, unpublished observation)." (PMID 17067392, 2006).
ovarian carcinoma (continued). "MOC often fail to express the ovarian cancer serum marker CA125 (MUC16), which is frequently elevated in the serum of patients with nonmucinous ovarian carcinoma." (PMID 16508639, 2006). "Considering that binding of both OC125 and M11 is required for the generation of a signal in the clinical immunoassay, this differential binding pattern may present a mechanism of undercounting MUC16 present in the serum of ovarian cancer patients." (PMID 40361385, 2025). "Interestingly, only Tumor 4 expressed MUC16, also known as CA125, the most widely used clinical diagnostic serum marker for ovarian cancer." (PMID 41279090, 2025). "For example, MUC16 (CA125) is widely used in ovarian cancer diagnostics." (PMID 41409294, 2025). "DMUC4064A: DMUC4064A targets MUC16, expressed in most epithelial ovarian cancers (EOCs), and may have anti-EOC activity." (PMID 40772179, 2025). "To confirm that the cytotoxic impact of MSLN-CAR T cells on ovarian cancer cells was dependent on MUC16 expression, we asked if forced expression of MUC16 in SKOV3 cells could lead to their cytotoxic killing." (PMID 38637885, 2024). "Thus, many additional ADCs against various targets, including NaPi2b, HER2/3, mesothelin, and MUC16, which are expressed in ovarian cancer, are under investigation." (PMID 38539161, 2024). "As tumors form, the glycosylphosphatidylinositol-anchored cell-surface protein known as mesothelin binds MUC16 at N-glycosylation sites to promote cancer cell adhesion, leading to metastatic activation of tumors, including mesothelioma and ovarian cancer, in the pleura and peritoneum." (PMID 38637885, 2024). "CA125, also known as MUC16, is implemented as a biomarker in the clinic for ovarian cancer." (PMID 39767713, 2024). "MUC16 is a commonly employed biomarker to identify and predict ovarian cancer (OC)." (PMID 39206405, 2024). "In addition, variable MUC16 can help ovarian cancer cells avoid immune cytotoxicity and form metastases." (PMID 39219440, 2024). "Our results suggest that ligand-receptor-based CAR T cell therapy that is designed to exploit the interaction between mesothelin and MUC16 may be effective as an ovarian cancer treatment." (PMID 38637885, 2024). "One significant challenge for current antibody-based cancer therapies that target MUC16-expressing tumors is the fact that the majority of the extracellular domain of MUC16 is cleaved and secreted, limiting the efficacy of MUC16 as a target antigen for ovarian cancer." (PMID 38637885, 2024). "Moreover, the classical ovarian cancer (OC) biomarkers CA125 (also known as Mucin-16 or MUC-16), HE4, and C5a were found in serum-derived EVs from epithelial OC patients providing greater diagnostic potential than their detection in serum alone." (PMID 39147028, 2024). "In addition, the combination of TTR and APOA1 with MUC16 and TF has shown a 96% overall sensitivity for early detection of ovarian cancer." (PMID 40836974, 2024). "Expression of MUC16 is elevated in epithelial ovarian cancer." (PMID 38758220, 2024). "Innovations in ovarian cancer treatment targeting MUC16 have shown potential." (PMID 38361923, 2024). "Because of this, we see a potential impact from MUC16 in malignancies beyond ovarian cancer." (PMID 39767713, 2024). "We note that MUC16 is not only expressed by ovarian cancer cells." (PMID 38197671, 2024). "Additionally, higher levels of proteins in ovarian cancer-derived exosomes that have diagnostic potential include CD24, CRABP2, MUC16, MSLN, soluble form of activated leukocyte cell adhesion molecule, and soluble E-cadherin." (PMID 38796525, 2024). "Mucin 16 (MUC16) is a mucin glycoprotein frequently overexpressed in epithelial ovarian cancer." (PMID 38667465, 2024). "Thus, our MSLN-CAR T cell approach shows specificity for MUC16 overexpression in ovarian cancer cells that drives their effective killing in vitro." (PMID 38637885, 2024).
ovarian carcinoma (continued). "Importantly, the levels of MUC16 in blood serum are regularly monitored in ovarian cancer patients, and an increase in its concentration from an individualized baseline level is considered a prognostic indicator of cancer recurrence." (PMID 38956143, 2024). "Combination of MSLN and MUC16 mediated adhesion in ovarian cancer." (PMID 38628720, 2024). "CA125, or MUC16 protein, is a high molecular weight glycoprotein on the cell surface characteristic of ovarian cancer, fallopian tube cancer, endometrial cancer, cervical cancer, pancreatic cancer, liver cancer, lung cancer, and digestive tumors, according to the literature." (PMID 38672729, 2024). "In ovarian cancer immunoregulation research, MUC16 plays a critical role, as evidenced by studies." (PMID 38361923, 2024). "Thus, the specificity of MSLN-CAR T cells for ovarian cancer cells is related to such cells expressing high levels of MUC16." (PMID 38637885, 2024). "The Indian Cohort showed MUC16, MUC4, and CIITA to be most mutated and carry CNV in the same genes apart from MYC, which is known to be amplified in most cancers, including ovarian cancer." (PMID 37091785, 2023). "MUC16 has been used as an ovarian cancer biomarker for several years." (PMID 37664708, 2023). "The expression of MUC16 has been documented in a high percentage of ovarian cancer cases." (PMID 38146364, 2023). "Previously, MUC16 autoantibodies have been detected in ovarian cancer patients." (PMID 36980526, 2023). "MUC16 (CA125) is a commonly used tumor marker for ovarian cancer screening and reported to be an immunosuppressive factor by acting on the sialic acid-binding immunoglobulin-like lectin-9 (Siglec-9) on the surface of natural killer cells (NK cells), B cells, and monocytes." (PMID 37644468, 2023). "Ultimately, Chekmasova and colleagues asserted that such encouraging outcomes could be the foundation of future clinical investigations with patients diagnosed with MUC16-positive ovarian cancer." (PMID 38146364, 2023). "Specifically, upregulation of MMP7 can be triggered by the interaction between the carboxy-terminal portion of the MUC16/CA125 protein expressed in ovarian cancer cells and mesothelin present on mesothelial cells, leading to an increase in invasive tumor properties and peritoneal carcinomatosis." (PMID 37569592, 2023). "To explore whether the alterations in the immunophenotype of neutrophils induced by ovarian cancer organoids were mediated by MUC16, we treated neutrophils with 100 μg/ml MUC16 protein and examined the immunophenotype of neutrophils." (PMID 37644468, 2023). "Similarly, elevated MUC16 expression is a predictor of disease progression as well as poor survival in ovarian cancer patients." (PMID 36980526, 2023). "These ADCs have been directed against specific antigens expressed in several solid tumors including ovarian cancer, among which the most investigated are cancer antigen 125 (CA125 or MUC16), NaPi2b, Trop2, TF, protein tyrosine kinase 7 (PTK7), CD166 and Notch3." (PMID 36046840, 2022). "MUC16 is overexpressed in epithelial ovarian cancer and used as a biomarker (CA125)." (PMID 35038288, 2022). "Elevation of CA125/MUC16 in serum is detected in ~80% of epithelial ovarian cancers." (PMID 36559316, 2022). "Mucin 16 (MUC16) is a glycoprotein that is highly expressed in ovarian cancer cells." (PMID 35754835, 2022). "Oregovomab is a mouse mAb that targets MUC16 in advanced ovarian cancer." (PMID 35628495, 2022). "MUC16 is mainly known as a routinely used tumor marker CA-125 in ovarian cancer." (PMID 35389164, 2022). "Reporter assays indicate that this DNA fragment possesses transactivation activity in CA-125-high cancer cells, but not in CA-125-low cancer cells, indicating that the DNA fragment contains the transactivation region that controls specific expression of the MUC16 gene in ovarian cancer cells." (PMID 34503075, 2021).
ovarian carcinoma (continued). "Based on our study findings, targeting MUC16 transactivation utilizing CRAd may now represent a feasible approach for ovarian cancer treatment." (PMID 34503075, 2021). "Similarly, a MUC16 × CD28 BsAb enhances the antitumor efficacy of CD3 BsAbs in a xenograft model of ovarian cancer." (PMID 34358141, 2021). "It was found that intravenous or intraperitoneal injection of MUC16-CAR-T cells could decline ovarian cancer progression completely or eradicated malignant cells in mouse models." (PMID 33494834, 2021). "Clinically, MUC16-CAR-T therapy was evaluated in recurrent platinum-resistant ovarian cancer." (PMID 33391401, 2021). "MUC16 has previously been shown to generate a Treg-attracting fragment after proteolysis, which has previously been shown to result in tumor aggressiveness in ovarian cancers." (PMID 34681642, 2021). "Circ_MUC16 was downregulated in Propofol-treated ovarian cancer cells." (PMID 34837947, 2021). "In addition, active MMP-14 promotes ectodomain shedding of MUC16/CA125 in ovarian cancer cells, restrains adhesion and promotes invasion of cancer cells in the peritoneum." (PMID 35047406, 2021). "Besides, we uncovered the interactions among circ_MUC16, miR-1182 and S100B, aiming to provide a potential mechanism of circ_MUC16 in Propofol-mediated ovarian cancer progression." (PMID 34837947, 2021). "MUC16 can promote tumorigenesis in ovarian cancer and play a role in tumor proliferation." (PMID 33867349, 2021). "Elevated levels of MUC16 in the blood serves as a prognostic biomarker for ovarian cancer." (PMID 33680922, 2020). "The presence of tumor cells in these samples was confirmed by qPCR analysis of the ovarian cancer marker genes MUC16 and HE4, while five of the nineteen cell samples were additionally analyzed for cell surface expression of mucin-16 and epithelial cell adhesion molecule (EpCAM) by flow cytometry." (PMID 33584686, 2020). "MUC16 is the most commonly presented peptide antigen in ovarian cancer." (PMID 32937961, 2020). "Less precise targeting of soluble or membrane bound MUC16 and other elements of the ovarian cancer TME, may be provided by alternatives to i.p. sialidase enzyme-antibody conjugate treatment." (PMID 32937961, 2020). "Heterotypic (cancer cell to mesothelial cell) interactions of mesothelin (MSLN) and its binding partner MUC16, which is the membrane-bound form of the ovarian cancer serum tumor marker CA-125 are important for attachment of cancer cells to the mesothelial layer." (PMID 32780245, 2020). "In addition, active MT1-MMP facilitates the shedding of ectodomain of MUC16/CA125 in ovarian cancer which restrains adhesion and invasion of cancer cells to the peritoneum." (PMID 33023532, 2020). "The presence of TAG72 has been confirmed on MUC1 and CD44 (an ovarian cancer stem cell marker and receptor for the ECM molecule hylauronan) as well as CD133 (a marker present in cancer stem-cells including ovarian cancer) and MUC16 proteins in ovarian cancer patients." (PMID 32937961, 2020). "Two well-studied TAAs for PDAC and ovarian cancer, MUC16, and CEACAM5, illustrate the two principal challenges of targeting non-mutated TAAs: difficulty in breaking T-cell tolerance and, conversely, the potential for induction of on-target off-tumor toxicities." (PMID 33087697, 2020). "Other than MUC16, ovarian cancer cells also overexpress MUC1, MUC9, and MUC13." (PMID 32785160, 2020). "MUC16 has been identified as the most highlt expressed antigen in ovarian cancer." (PMID 32698888, 2020). "In fact, MUC family member has been viewed as ideal target for CAR‐T cells in various cancers: CAR‐T cell therapy specific for MUC1 has been clinically tested in HCC, breast and glioma 25; CAR‐T cells specific for MUC16 have also being investigated in ovarian cancer." (PMID 32596961, 2020).
ovarian carcinoma (continued). "Specifically, we showed that MUC16 knockdown in ovarian cancer cells significantly decreased tumorigenicity, whereas the enforced expression of MUC16 C-terminal domain (last 284 C-terminal residues) enhanced soft agar colony formation and tumor growth in nude mice." (PMID 31039761, 2019). "The MUC16-mesothelin interaction is capable of activating MUC16, thus enhancing ovarian cancer cell metastasis and the epithelial mesothelial to mesenchymal transition, suggesting that the binding of these proteins triggers pathways that regulate cellular adhesion and motility." (PMID 31514468, 2019). "Next, we determined the dose responsiveness of MUC16 secretion to ovarian cancer ascites." (PMID 31039761, 2019). "Given the role of MUC16 in ovarian cancer progression, identifying factors that regulates its expression may provide new avenues for ovarian cancer treatment." (PMID 31039761, 2019). "The MUC16 gene, also called CA125, was recently shown to play a pivotal role in promoting ovarian cancer growth and metastasis and is associated with a higher tumor mutation load (TML), better survival outcomes and better immune response in patients with gastric cancer." (PMID 31822636, 2019). "Collectively, these data indicate that mesothelial cells are an important source of MUC16 in the context of ovarian cancer and malignant ascites is a strong modulator of MUC16 expression in HPMCs and uncover the Akt pathway as a driving factor for upregulation of MUC16." (PMID 31039761, 2019). "OVCAR-3 cells are ideally suited for dissecting the function of MUC16 since these cells express comparable amounts of surface expressed MUC16 as seen in ovarian cancer patients, maintain an epithelial phenotype and have been extensively used in several studies involving MUC16." (PMID 29708979, 2018). "Because cancer cells in which MUC16 was overexpressed have been shown to be resistant to cisplatin in ovarian cancer, we also treated the cultured cells with cisplatin after the MUC16 gene was edited, and MUC16 overexpression induced resistance to cisplatin in the lung cancer cells." (PMID 29552305, 2018). "In addition, MUC16 is involved in ovarian cancer development and has been applied in targeted therapy against ovarian cancer, including CA125 antibodies." (PMID 29542355, 2018). "Although MUC16 was initially believed to be a specific biomarker of ovarian cancer, MUC16-related studies have clarified that this marker can also be detected in the sera of patients that have other types of cancer, including pancreatic cancer, colorectal cancer, and gastric adenocarcinoma." (PMID 29552305, 2018). "The monoclonal antibody OC125/Mab anti-MUC16 identifies this tumor-associated antigen, which is over-expressed in epithelial ovarian cancer cells, but not in the epithelium of normal fetal and mature ovaries." (PMID 30287783, 2018). "In previous studies, MUC16 up-regulation was shown to contribute to the invasion, aggression, and metastasis of tumor cells in various cancer types, particularly in ovarian cancer." (PMID 29552305, 2018). "The optimum nanomicelle formulation was surface-functionalized with anti-MUC 16 (antibody) for the targeted delivery of methotrexate to human ovarian carcinoma (NIH:OVCAR-5) cells in Athymic nude mice that expressed MUC16, as a preferential form of intraperitoneal ovarian cancer (OC) chemotherapy." (PMID 30287783, 2018). "Additionally, MUC16 is also considered to be a gold standard marker for monitoring ovarian cancer recurrence." (PMID 29552305, 2018). "Furthermore, MUC16 up-regulation has been shown to correlate with ovarian cancer relapse and poor prognosis." (PMID 29552305, 2018). "These antibodies can serve as valuable reagents for understanding MUC16 cleavage and may also serve as potential therapeutic agents for treatment of ovarian cancer." (PMID 29708979, 2018).